MIR101-2 (microRNA 101-2)
Synonyms: hsa-mir-101-2; MIRN101-2; mir-101-2
Gene: MicroRNA gene on chromosome 9 (4,850,297 to 4,850,375, forward strand). Ensembl gene ENSG00000199065.
Gene Ontology:
Biological process: miRNA-mediated post-transcriptional gene silencing
Cellular component: RISC complex
Homologues: Orthologues: chimpanzee ptr-mir-101-2 (100% identical), macaque MIR101-2 (100% identical), pig ssc-mir-101-1 (100% identical), rabbit MIR101-2 (100% identical), guinea pig MIR101-2 (99% identical), rat Mir101-2 (97% identical), tropical clawed frog xtr-mir-101a-1 (96% identical), zebrafish mir101b (82% identical). Paralogues in human: MIR101-1 (75% identical).